WFS1 (wolframin ER transmembrane glycoprotein)
Diseases named in the same sentence as WFS1 in open-access papers (continued):
Sharing a sentence is not in itself a finding about the gene and the disease.
diabetes (continued). "Co-occurrence of diabetes and deafness in maternal aunts led to discovery of WFS1 (Wolfram syndrome type 1) as a cause of non-syndromic deafness in multiple members of the maternal pedigree." (PMID 34630320, 2021). "Previous case report found some pathogenic variants of WFS1(p.Trp314Arg, p.Leu829Pro), particularly dominant variants, cause deafness or diabetes alone." (PMID 33879153, 2021). "Patients with Wolfram syndrome, an autosomal recessive disorder that is caused by WFS1 mutations, develop childhood diabetes as a result of beta cell ER stress." (PMID 33477961, 2021). "This work identifies a vesicular cargo receptor for ER export and suggests that impaired peptide hormone transport underlies diabetes resulting from pathogenic WFS1 mutations." (PMID 34848728, 2021). "Variants of WFS1 are also associated with non-syndromic hearing loss and type-2 diabetes mellitus (T2DM)." (PMID 31937257, 2020). "WFS1 is the most common causative gene in Wolfram-like syndrome, a rare autosomal dominant disease characterized by congenital progressive hearing loss, diabetes mellitus, and optic atrophy." (PMID 32883240, 2020). "Two other heterozygous genotypes in the WFS1 gene (rs10010131 SNP and rs6446482 pathogenic SNPs) have also previously been shown to be associated with Type 2 Diabetes Mellitus." (PMID 31604968, 2019). "In contrast, two other patients (patients # 16 and 77) had biallelic WFS1 variants and presented with OA but also had type 2 diabetes mellitus (T2DM) and a positive family history of hearing loss, respectively." (PMID 31765440, 2019). "Another two heterozygous variants were associated with Non-insulin Dependent Diabetes Mellitus located within the WFS1 gene; rs10010131 and rs6446482." (PMID 31604968, 2019). "The similarity of cellular stress response in beta cells and in neurons highlights the value of the Wfs1 KO rat as a pre-clinical tool not only to find treatment strategies for diabetes mellitus but also for ER stress-associated neurodegenerative diseases." (PMID 31673100, 2019). "We identified six children with monogenic diabetes, including four novel mutations: homozygous mutations in WFS1 (n=3), SLC19A2 and SLC29A3, and a heterozygous mutation in GCK." (PMID 31276222, 2019). "Some heterozygous mutations in WFS1 can cause Wolfram-like syndrome, which is characterized by autosomal dominant inherited HL with optic atrophy and/or diabetes mellitus." (PMID 29529044, 2018). "Although loss-of-function mutation in WFS1 is related to autosome-recessive WS, a mutation in WFS1 was also believed to be a cause of autosome-dominant OA, hearing impairment, and diabetes." (PMID 29483894, 2018). "The loss of beta cells and the accompanying development of diabetes mellitus require 5–6 years in human WS patients and only 1 year in Wfs1-ex5-KO232 rats." (PMID 28860598, 2017). "(2013) identified a single‐missense WFS1 mutation (p.Trp314Arg) segregating with diabetes in a multigeneration Finnish family." (PMID 28432734, 2017). "The presence of minor loss‐of‐function variants in WFS1 predicted isolated diabetes, isolated deafness, or isolated congenital cataracts without development of the full syndrome (sensitivity 100% [93%–100%]; specificity 78% [73%–82%])." (PMID 28432734, 2017). "Polymorphisms of the WFS1 was suggested as a minor modulator of gene function, and susceptibility to polygenic forms of diabetes." (PMID 29988211, 2017). "WFS1 is a new susceptible diabetes gene, which has been confirmed recently with genome wide association, and replication studies." (PMID 29988211, 2017). "The most significantly downregulated gene associated with insulin secretion and diabetes in WFS1‐deficient islets following Wfs1 was melastatin‐related transient receptor potential subfamily member 5 (Trpm5)." (PMID 27053292, 2016). "Association analysis of the investigated WFS1 SNPs and diabetes mellitus by Cochran–Armitage trend test." (PMID 26426397, 2015).
diabetes (continued). "Our earlier study revealed that miR-668 not only bound to the 3’ UTR of the WFS1 gene, but this connection was influenced by the rs1046322 SNP, which showed a significant association with diabetes mellitus according to our current findings." (PMID 26426397, 2015). "Genotype-wise association analysis of the investigated WFS1 SNPs and diabetes mellitus using recessive model." (PMID 26426397, 2015). "In this study we demonstrate an association between both types (T1DM and T2DM) of diabetes mellitus and SNPs in the WFS1 gene." (PMID 26426397, 2015). "Genotype-wise association analysis of the investigated WFS1 SNPs and diabetes mellitus using dominant model." (PMID 26426397, 2015). "All had confirmed mutations on the WFS1 gene and had insulin dependent diabetes mellitus (average age of onset = 5.8 years; range 2–14 years of age)." (PMID 22792385, 2012). "Novel variants in the genes ARAP1, GLIS3, MADD, NOTCH2 and WFS1 need further investigation to reveal their possible role in diabetes." (PMID 22662265, 2012). "Mutations in WFS1 are also responsible for other conditions such as psychiatric disorders and diabetes mellitus (Lesperance laboratory database)." (PMID 20069065, 2010). "The WFS1 mutant disrupts the receptor splice site and affects the pattern of mRNA splicing, which leads to β‐cell apoptosis and promotes β‐cell dedifferentiation and loss of normal insulin secretion, leading to diabetes." (PMID 40641032, 2025). "Four heterozygous WFS1 mutations were identified in three diabetes families." (PMID 40641032, 2025). "Similarly, a recent report describes a Pakistani child who acquired cataracts at age 3, subsequently developed systemic manifestations of diabetes mellitus 2 years later, and harbored a different, novel, heterozygous WFS1 variant." (PMID 40995355, 2025). "This case provides real-world evidence that rapid WFS1-related cataract development may result from the underlying condition in conjunction with or independent from WFS1-associated diabetes mellitus." (PMID 40995355, 2025). "These mutations may indicate a role of WFS1 in the pathogenic mechanism of diabetes, and alternative treatments should be investigated." (PMID 40641032, 2025). "Most cases of visual impairment caused by WFS1 variants are detected through eye examinations conducted after the diagnosis of diabetes mellitus or diabetic ketoacidosis in adolescents and genetic testing that confirms the presence of pathogenic variants in the WFS1 gene." (PMID 39423307, 2025). "This case provides evidence that rapid WFS1-related cataract development may result from the underlying condition perhaps in conjunction with WFS1-associated diabetes mellitus." (PMID 40995355, 2025). "However, other heterozygous variants in the WFS1 gene are suspected to have an association with diabetes mellitus." (PMID 39858604, 2025). "Moreover, the largest WFS1‐associated diabetes pedigree to date was reported, showing a genetic pattern consistent with MODY." (PMID 40641032, 2025). "A retrospective analysis was conducted, including patients’ age, sex, consanguinity, age at symptom onset, diagnosis of diabetes mellitus, optic atrophy, diabetes insipidus, neurological and psychiatric disorders, hearing loss, urinary disorders, hypogonadism, and WFS1 molecular analysis." (PMID 39420940, 2024). "There are data in the literature of WFS1 variants associated with different diabetes phenotypes." (PMID 39201476, 2024). "This suggests that while WFS1 compound heterozygous variants impair ER calcium stability and cell viability, they do not significantly heighten β-cell death, providing insights into the cellular effects of WFS1 variants in diabetes." (PMID 39221226, 2024). "Furthermore, one of the variants (c.2054G>A) was mentioned in a study on early-onset diabetes in a Chinese population, where a patient with diabetes with this variant also had another pathogenic variant in the WFS1 gene." (PMID 39766859, 2024).
diabetes (continued). "The pathogenic variation of WFS1 is closely related to the occurrence and development of diabetes." (PMID 36967753, 2023). "Our findings suggest a role for WFS1 in obesity, which is a risk factor for diabetes." (PMID 37859980, 2023). "However, previous studies have linked several WFS1 SNPs with type 2 diabetes and biomarkers related to diabetes across various ethnicities, including the United Kingdom population, Swedish population and Ashkenazi population." (PMID 37859980, 2023). "WFS1 is a membrane protein that is vital for the transfer of vesicular cargo proteins from the endoplasmic reticulum to the Golgi apparatus and is associated with diabetes." (PMID 36830826, 2023). "The WFS1 protein is highly expressed in islet endothelial cells, and genome-wide association studies have found that WFS1 is an important susceptibility gene for diabetes." (PMID 37974252, 2023). "It has been suggested that miRNA binding sites on WFS1 play a critical role in the regulation of the wolframin protein, and loss of WFS1 function may lead to the pathogenesis of diabetes." (PMID 37859980, 2023). "Furthermore, we identified a novel heterozygous, likely pathogenic, missense mutation in WFS1 (p.V142L) inherited from the father with diabetes." (PMID 35227307, 2022). "Here, we hypothesized that the likely pathogenic heterozygous variant in WFS1 might possibly explain the patient's early-onset diabetes and the efficacy of GLP1-RA on prandial insulin interruption." (PMID 35227307, 2022). "A recent study has shown that GLP1-RA could be efficient for patients with diabetes and heterozygous, pathogenic WFS1 variants." (PMID 35227307, 2022). "There may be the recessive mutations involved, as reported in China for the early onset of diabetes due to non-syndromic recessive WFS1 mutations." (PMID 34763692, 2021). "Both maternal aunts with deafness and diabetes carried a novel mutation in the WFS1 gene." (PMID 34630320, 2021). "Therefore, our data indicated that the impaired transport of vesicular cargo proteins underlies diabetes caused by WFS1 pathogenic mutations." (PMID 34848728, 2021). "The Wfs1‐null mice exhibit progressive insulin deficiency and diabetes." (PMID 27053292, 2016). "It was suggested that polymorphisms of the WFS1 resulting in minor modulation of the gene function instead of complete loss might be in the genetic background of the common, polygenic forms of diabetes (T1DM and T2DM)." (PMID 26426397, 2015). "Allele-wise association analysis of the investigated WFS1 SNPs and diabetes mellitus." (PMID 26426397, 2015). "For example, individuals who are carriers for pathogenic variants in the Wolfram syndrome 1 (WFS1) gene, may exhibit low frequency sensorineural hearing loss and/or diabetes mellitus." (PMID 25714468, 2014). "Interestingly, treatment of Wfs1 KO mice with pioglitazone was found to reduce β cell loss and protect mice from diabetes." (PMID 21050479, 2010). "Although WFS1 pathogenic variants related to the classic syndromic phenotype are inherited in recessive mode, dominantly acting variants can determine so-called “Wolfram-like” phenotypes, characterized by low-frequency hearing impairment, diabetes mellitus, and/or optic atrophy." (PMID 40332750, 2025). "The clinical features of this family were consistent with the MODY genetic profile, supporting the conclusion that the WFS1 c.985T>A/p.F329I mutation may act as a pathogenic factor for diabetes in this family, following an autosomal dominant inheritance pattern." (PMID 40641032, 2025). "Some reports are suggesting that WFS1 can also cause diabetes in an autosomal dominant mode, that WFS1 heterozygous variants can also cause WS, and that WFS1 compound heterozygous variants can also cause diabetes only, complicating genotype-phenotype correlations and risking misdiagnosis." (PMID 39221226, 2024). "The clinical phenotypes of patients with isolated diabetes caused by WFS1 variations are similar to those of our patients with WFS1-DM." (PMID 37277527, 2023).
diabetes (continued). "Heterozygous mutations in WFS1 have also been associated with non-syndromic diseases characterized by isolated hearing loss, diabetes or congenital cataract, and with Wolfram-like syndrome, characterized by progressive hearing impairment, diabetes mellitus, and optic atrophy." (PMID 33806088, 2021). "Moreover, it was also demonstrated that WFS1 regulates secretory granule acidification in β-cells and neurons and that the ER dysfunction caused by WFS1 deficiency is accompanied by altered mitochondrial function in β-cells and neurons contributing to diabetes and neurodegeneration." (PMID 34992533, 2021). "In addition to diabetes mellitus and insipidus with optical atrophy, and hearing impairment (HI), individuals with variants in WFS1 also can present with intellectual development disorder, and cerebellar ataxia, along with osseous, renal, and cardiac abnormalities." (PMID 33879837, 2021). "On the other hand, the genetic test for WFS1 may allow early diagnosis even before the onset of diabetes mellitus or diabetes insipidus in patients with hearing loss, vision defects, family history, and so on, if there is an index of suspicion for this disorder." (PMID 25211237, 2014). "Syndromic Diabetes: Arises from mutations in pleiotropic transcription factors (GLIS3, GATA6, HNF1B) or metabolic transporters (SLC19A2, WFS1)." (PMID 41614934, 2026). "In conclusion, WFS1-related diabetes represents a prototype of “conformational diseases” where protein misfolding drives organ failure." (PMID 41614934, 2026). "Diabetes mellitus was present in all cases except one patient with an autosomal dominant WFS1-related disorder." (PMID 40647593, 2025). "WFS1 spectrum disorder is a rare condition, characterized by diabetes insipidus, diabetes mellitus, optic atrophy, and deafness (DIDMOAD)." (PMID 40995355, 2025). "The family of Proband C showed an apparent autosomal dominant inheritance pattern of adult diabetes, with WES identifying the c.985T>A/p.F329I mutation in the WFS1 gene." (PMID 40641032, 2025). "WFS1 spectrum disorder (WFS1-SD) is a rare genetic condition, characterized by diabetes insipidus, diabetes mellitus, optic atrophy, and deafness (DIDMOAD)." (PMID 40995355, 2025). "WFS1‐related diabetes typically has an early onset, with ~95% of cases manifesting before the age of 25, primarily affecting children and adolescents." (PMID 40641032, 2025). "Using the CTD, GeneCards, and GSEA databases, we identified WFS1 as a diabetes-related gene and then conducted an extensive investigation focusing on WFS1 in the context of EC." (PMID 39478865, 2024). "Collectively, our findings underscore the pivotal role of the diabetes-related gene WFS1 in EC diagnosis and prognosis evaluation, thus positioning WFS1 as a promising therapeutic target for the treatment of this condition." (PMID 39478865, 2024). "Other preclinical models were developed to recapitulate WS1, including a mouse and later a rat that lacks the exon 5 of Wfs1 (Wfs1−e5/−e5) and develops diabetes by nine months of age." (PMID 38542026, 2024). "Juvenile diabetes with declining vision and hearing in a child with developmental milestones characterizes the abnormal functioning of the WFS1 gene." (PMID 39767643, 2024). "We report the clinical and genetic characteristics of six patients with diabetes with WFS1 variation from three families and further explored their complex clinical phenotypes to deepen the understanding of the disease caused by gene variation." (PMID 36967753, 2023). "WFS1 also interacts with the insulin release-related proteins (HHEX and CDKAL1), which are strongly associated with genetic risk variants for diabetes." (PMID 37185285, 2023). "Here, we confirmed that the long-acting GLP-1R agonist dulaglutide also prevents and reverses glucose intolerance/diabetes in Wfs1 KO mice by enhancing beta cell function." (PMID 36995380, 2023).
diabetes (continued). "WFS1-related disorders involve a wide range of clinical phenotypes, including diabetes mellitus and neurodegeneration." (PMID 36967753, 2023). "Very briefly, we have identified the growth retardation and development of combined endocrine disorders, combined with diabetes, in WFS1 mutant mice." (PMID 37759745, 2023). "Regarding the pathomechanism of WS1 diabetes, it is known that the pancreatic β-cells highly express WFS1 gene." (PMID 36835101, 2023). "This mouse line very accurately recapitulated all aspects of WFS1, starting with the diabetes, infertility, eye problems, etc.." (PMID 37759745, 2023). "Wolfram syndrome, caused by autosomal recessive inheritance of biallelic variations in the wolframin (WFS1) gene, is another rare neurodegenerative disorder that initially presents as diabetes mellitus." (PMID 35805109, 2022). "Of the 34 gene panels for MODY/monogenic diabetes listed in the NCBI Gene Testing Registry, only six panels and one panel included WFS1 and SLC19A2, respectively (the two commonest causes in our Turkish cohort)." (PMID 34686905, 2022). "At the age of 11.5 months, 62.5% (10 out of 16) of the liraglutide-treated Wfs1 KO animals remained diabetes-free." (PMID 34831417, 2021). "Previous mouse models of WS involved only partial diabetes and other symptoms of the disease, whereas Wfs1 KO rats developed diabetes as well as neuronal degeneration, as do patients." (PMID 33959146, 2021). "They showed that these different pathways can be in the background of the same phenotype, as miR-185 is suggested to be related to diabetes mellitus via WFS1 target." (PMID 34925466, 2021). "miR-185 was reported to be strongly associated with diabetes mellitus via its targets SOCS3 and WFS1." (PMID 34925466, 2021). "At the age of 7.5 months, Wfs1 KO rats showed the first signs of diabetes by reduced c-peptide and insulin, and increased glucagon secretion (p < 0.01)." (PMID 34831417, 2021). "The PCS also highlighted several other highly scoring candidates with known causal roles in relation to diabetes and obesity such as MC4R (PCS = 0.43), WFS1 (0.41), ABCC8 (0.37), LEP (0.27), GCK (0.24) and HNF1A (0.23)." (PMID 30914061, 2019). "The progressive development of diabetes mellitus and other WS symptoms makes the Wfs1-ex5-KO232 rat a good tool to study treatment options." (PMID 29976929, 2018). "Common variants in the monogenic diabetes genes HNF4A and WFS1, and a low-frequency variant in the HNF1A gene have also been associated with risk for T2D, highlighting the genetic overlap between monogenic diabetes and T2D." (PMID 29207974, 2017). "Diabetes mellitus in male Wfs1-ex5-KO232 rats appears at approximately 1 year of age; at this age, the rat is an adult." (PMID 28860598, 2017). "Wfs1 mutant rats can also be used for translational research connected to other ER stress-related disorders, including diabetes and neurodegeneration." (PMID 28860598, 2017). "These Wfs1-ex5-KO232 rats show progressive glucose intolerance, which culminates in the development of diabetes mellitus, glycosuria, hyperglycaemia and severe body weight loss by 12 months of age." (PMID 28860598, 2017). "Although this study has some limitations, mainly regarding islet stimulation induction and sample size, in conclusion, mice with disrupted Wfs1 gene had fewer pancreatic islets and defective insulin secretion explaining their diabetes‐like phenotype." (PMID 27053292, 2016). "A genetic risk score based on the diabetes risk alleles TCF7L2 rs7903146, KCNQ1 rs163184, KCNQ1 rs2237892, GIPR rs10423928 and WFS1 rs10010131 also showed a nominally significant interaction with coffee intake (p = 0.005)." (PMID 27623947, 2016). "Looking for a mouse model for WS optic neuropathy, we analyzed visual function of Wfs1 knock-in mice modified in Wfs1 translation starting site and described as a model of type 1 diabetes mellitus with normoglycemia and hypoinsulinemia." (PMID 24823368, 2014).